C5orf46 (chromosome 5 open reading frame 46)
Synonyms: MGC23985; SSSP1; AP-64
Tractability: Antibody: UniProt places it where antibodies can reach, with high confidence; UniProt predicts a signal peptide or a membrane-spanning region; its Gene Ontology location is reachable by antibodies, with medium confidence.
Gene: Protein-coding gene on chromosome 5 (147,879,632 to 147,906,538, reverse strand). Ensembl gene ENSG00000178776.
Subcellular location: Secreted
Subcellular location (Human Protein Atlas): Nuclear speckles; Mitochondria; Predicted to be secreted
Gene Ontology:
Molecular function: protein binding
Cellular component: extracellular exosome; extracellular region
Genetic constraint (gnomAD): Loss-of-function variants: 4 observed, 4.49 expected, observed/expected ratio (o/e) 0.89, 90% interval 0.43 to 1.77. That is too few expected variants to judge how well the gene tolerates losing a copy. Missense variants: 63 observed, 68 expected, observed/expected ratio (o/e) 0.93, 90% interval 0.75 to 1.14. Synonymous variants: 23 observed, 24.53 expected, observed/expected ratio (o/e) 0.94, 90% interval 0.67 to 1.33.
Homologues: Orthologues: chimpanzee C5H5orf46 (99% identical), macaque C6H5orf46 (95% identical), dog C5orf46 (76% identical), mouse Gm94 (69% identical), pig C5orf46 (68% identical), rat C18h5orf46 (67% identical), guinea pig C5orf46 (54% identical).
Diseases named in the same sentence as C5orf46 in open-access papers:
C5orf46 is named in the same sentence as 17 diseases in open-access papers, as found by Europe PMC text mining. Sharing a sentence is not in itself a finding about the gene and the disease. The quoted sentences say what the papers report.
gastric cancer (2 papers, 2022 to 2025). A primary or metastatic malignant neoplasm involving the stomach. "C5ORF46 has been implicated in antibacterial activity and associated with patient prognosis in pancreatic cancer, colorectal cancer, and stomach cancer." (PMID 35991552, 2022). "It was found that molecules like DCLK1 and ADCYAP1 were downregulated, whereas THPO and C5orf46 were upregulated in gastric cancer." (PMID 41049174, 2025). "We found that molecules such as ABCA6, DCLK1, and ADCYAP1 were linked to higher risk, with DCLK1 and ADCYAP1 being downregulated, while THPO and C5orf46 were upregulated in gastric cancer tissues." (PMID 41049174, 2025). "Similarly, by analyzing the TCGA expression profile, C5ORF46 was found to be differentially expressed and have prognostic significance in the context of stomach cancer and colorectal cancer." (PMID 35991552, 2022).
colon adenocarcinoma (1 paper, 2022). "Several reports implicate C5ORF46 as having a pro-tumoral role with possible prognostic value in the development of pancreatic adenocarcinoma (PAAD), colon adenocarcinoma (COAD) and stomach adenocarcinoma (STAD), which underline the value of studying C5ORF46 in GI tumors." (PMID 35991552, 2022).
colorectal cancer (1 paper, 2022). A primary or metastatic malignant neoplasm that affects the colon or rectum. "C5ORF46 mRNA levels were found to be considerably increased in colorectal cancer and pancreatic cancer tissues compared to the corresponding normal tissues." (PMID 35991552, 2022).
pancreatic cancer (1 paper, 2022). "Further, the potential of exosomal C5ORF46 as a tumor marker in pancreatic cancer was uncovered by bioinformatics analyses using multiple ORF databases." (PMID 35991552, 2022).
cancer (2 papers, 2022 to 2026). A tumor composed of atypical neoplastic, often pleomorphic cells that invade other tissues. "Moreover, the association between C5orf46 and multiple critical cancer traits, including microenvironment angiogenesis, immune infiltration, ECM degradation, and cancer EMT, was validated." (PMID 42158413, 2026). "The role of aberrant C5ORF46 expression in cancer development, patient prognosis, and cancer immunity was revealed in this study, and warrants further exploration." (PMID 35991552, 2022). "To further study the relationship of C5ORF46 and cancer immunity, we focused on the relationship between C5ORF46 expression and the infiltration of 22 types of immune-related cells." (PMID 35991552, 2022). "Liver demonstrated stronger C5ORF46 staining in cancer tissues than in normal tissues." (PMID 35991552, 2022). "Given that endoplasmic reticulum stress and calcium dysregulation are closely related to inflammatory responses and cancer immunity, we postulated that C5ORF46 may play a critical role in cancer inception and development." (PMID 35991552, 2022). "Fourthly, despite C5ORF46 expression being shown to be substantially linked to immune cell infiltration and cancer prognosis in humans, there is no direct evidence that C5ORF46 influences prognosis by participating in immune infiltration." (PMID 35991552, 2022). "Hence, the mechanisms by which C5ORF46 participates in cancer progression and immune regulation remain to be clarified." (PMID 35991552, 2022). "However, with limited evidence, the role of C5ORF46 in cancer development remains unexplained." (PMID 35991552, 2022). "Then, based on gene expression as well as survival analysis results, C5orf46 was shown to be upregulated in various human cancers, wherein KIRC showed the greatest difference in C5orf46 expression between cancer and corresponding normal tissues." (PMID 42158413, 2026). "Although the types of C5ORF46 alteration were diverse and differed across cancers, in patients with CHOL and PAAD, who had the highest frequency of C5ORF46 CNV alteration, all the alterations were amplification." (PMID 35991552, 2022). "The differential expression of C5ORF46 was examined with Oncomine, Tumor Immune Estimation Resource (TIMER), Gene Expression Profiling Interactive Analysis (GEPIA), Cancer Cell Line Encyclopedia (CCLE), the Human Protein Atlas (HPA) and TCGA databases." (PMID 35991552, 2022). "Further, C5ORF46 presented as an important regulator in the tumor microenvironment (TME) and was active in the regulation of cancer immune functions." (PMID 35991552, 2022).
tumor (2 papers, 2022 to 2026). "We used the bioinformatics analyses based on the TCGA database to analyze tumor mutational burden (TMB), microsatellite instability (MSI), tumor immune cell infiltration, and the correlations between C5ORF46 expression and several immune-related genes." (PMID 35991552, 2022). "Our study demonstrated that, in GI tumors, C5ORF46 had a strong association with tumor-infiltrating immune cells, particularly neutrophils." (PMID 35991552, 2022). "The results show that C5ORF46 was significantly upregulated in all the GI tumors compared to tumor-adjacent tissues (p < 0.05)." (PMID 35991552, 2022). "In this study, we used multiple databases to analyze differences in C5ORF46 expression levels between GI tumor tissues and tumor-adjacent normal tissues, and in various cell lines." (PMID 35991552, 2022). "Consistently, we demonstrated that C5ORF46 was highly expressed in tumor tissues compared to normal tissues in human GI tumors." (PMID 35991552, 2022). "In contrast to the Oncomine results, C5ORF46 levels in PAAD were lower in tumor tissues than in tumor-adjacent normal tissues, although at insignificant levels." (PMID 35991552, 2022). "In this study, we first analyzed C5ORF46 expression between tumor and tumor-adjacent normal tissues." (PMID 35991552, 2022). "In concert, our IHC results performed on clinical sections show increased C5ORF46 protein levels in all the seven GI tumors compared to tumor-adjacent normal tissues." (PMID 35991552, 2022). "Relative C5ORF46 expression levels in tumor cell lines were presented according to tissue origin across 24 tissue cell lines using the data from the CCLE database." (PMID 35991552, 2022). "We discovered that C5ORF46 expression is related to tumor stage in COAD, ESCA, LIHC, PAAD, and READ." (PMID 35991552, 2022). "To further verify our bioinformatics results, we evaluated C5ORF46 expression in clinical GI tumor and tumor-adjacent tissues using IHC." (PMID 35991552, 2022). "We separated the TCGA tumor samples into two groups with high and low C5ORF46 expression levels and analyzed the main terms of GO BP and KEGG pathway by GSEA to examine the influence of C5ORF46 gene expression on GI tumors." (PMID 35991552, 2022).
GI tumors (1 paper, 2022). "We investigated the associations between C5ORF46 expression and immune checkpoint genes in seven GI tumors." (PMID 35991552, 2022). "In concert with previous studies, high C5ORF46 expression correlated significantly with poor prognosis in GI tumor patients." (PMID 35991552, 2022). "Further, we used correlation and enrichment analysis of C5ORF46 and immune-related genes to study the biological functions of C5ORF46 in GI tumors." (PMID 35991552, 2022). "We carried out a survival association analysis for each GI tumor, including OS, DSS/DFS, and PFI, to investigate the relationship between C5ORF46 expression level and prognosis in GI tumors." (PMID 35991552, 2022). "Our results show that the expression of C5ORF46 was significantly upregulated in all seven GI tumor tissues compared with normal tissues." (PMID 35991552, 2022). "According to the TIMER database, the expression levels of C5ORF46 were considerably higher in GI tumor tissues, namely CHOL, COAD, ESCA, LIHC, READ, and STAD." (PMID 35991552, 2022). "In supplementary results, TCGA and GTEx databases were integrated using R software to further analyze the expression pattern of C5ORF46 in GI tumors." (PMID 35991552, 2022). "We found C5ORF46 expression displayed significant difference between stages I and II in five out of seven types of GI tumor, including COAD (p = 0.018), ESCA (p = 0.0014), LIHC (p = 0.026), PAAD (p = 0.014), and READ (p = 0.0031)." (PMID 35991552, 2022). "To further validate our results, we conducted IHC staining to examine the expression of C5ORF46 in GI tumor samples." (PMID 35991552, 2022). "Using Spearman’s rank correlation coefficient, the correlation of C5ORF46 expression with TMB was statistically examined for each GI tumor type independently." (PMID 35991552, 2022). "Further, according to the ESTIMATE results, C5ORF46 was positively related with immune and stromal scores in GI tumors, especially COAD, which indicated an increased ratio of corresponding components in the TME." (PMID 35991552, 2022). "We examined the relationship between C5ORF46 expression and the levels of infiltration of 22 immune-related cells in GI tumors using CIBERSORT." (PMID 35991552, 2022). "We performed KEGG pathway enrichment analysis on the genes that display similar expression patterns to C5ORF46 in GI tumors." (PMID 35991552, 2022). "The results indicate that genetic changes of C5ORF46 were present in 0.6% of GI tumor patients based on data from TCGA, of which amplification was the most common type." (PMID 35991552, 2022). "Our results reveal that C5ORF46 is a potential prognostic and immunological marker for GI tumors." (PMID 35991552, 2022). "Immunohistochemistry (IHC) was used to validate the expression of C5ORF46 in GI tumors." (PMID 35991552, 2022). "Consequently, further research into the link between TME and C5ORF46 expression in GI tumors is needed." (PMID 35991552, 2022). "Similarly, previous studies suggested a pro-tumoral and prognostic role of C5ORF46 in several GI tumors, including PAAD, COAD, and STAD." (PMID 35991552, 2022). "Together, these results suggest that C5ORF46 expression might play an essential role in human GI tumors by regulating inflammation and immune responses." (PMID 35991552, 2022). "The expression levels of C5ORF46 were significantly higher in stage II than in stage I. Intriguingly, most of the GI tumors tended to have the lowest expression levels of C5ORF46 in stage I. We found that C5ORF46 expression was particularly higher in younger patients (age ≤65) in ESCA." (PMID 35991552, 2022). "Of the five GI tumors with statistical significance between C5ORF46 expression and disease stage, in all cases, stage II presented a higher C5ORF46 expression level compared with stage I. COAD (p = 0.033) and ESCA (p = 0.011) demonstrated differential C5ORF46 expression between stages I and III." (PMID 35991552, 2022).
GI tumors (continued). "Using TCGA datasets, we assessed the prognostic validity of C5ORF46 in seven GI tumors." (PMID 35991552, 2022). "Relationship between C5ORF46 expression and immune cell infiltration in GI tumors." (PMID 35991552, 2022). "It is possible, therefore, that C5ORF46 may be a predictive marker for GI tumors." (PMID 35991552, 2022). "We postulated that C5ORF46 may be a potential prognostic marker for human GI tumors." (PMID 35991552, 2022). "However, the prognostic and immunological value of C5ORF46 in human GI tumors remains largely unknown." (PMID 35991552, 2022). "Therefore, C5ORF46 may be a possible prognostic indicator molecule in GI tumors." (PMID 35991552, 2022). "This gave a hint of how C5ORF46 could participate in maintaining the TME and the progression of GI tumors." (PMID 35991552, 2022).
C5orf46 also shares sentences with these, for which no sentence is quoted: meningitis (2 papers); autoimmune thyroid disease (1); bacterial meningitis (1); glioblastoma (1); infection (1); leishmaniasis (1); pancreatic adenocarcinoma (1); stomach adenocarcinoma (1); stomach cancer (1); viral infections (1).